STAT3 (signal transducer and activator of transcription 3)
Diseases named in the same sentence as STAT3 in open-access papers (continued):
Sharing a sentence is not in itself a finding about the gene and the disease.
endometrial cancer (continued). "In addition, the loss of STAT3 will weaken the invasion of EMT and endometrial cancer induced by the down-regulation of miR-20a-5p, and is vital for endometrial cancer metastasis and malignant transformation." (PMID 35577802, 2022). "In addition to the classical JAK‐STAT pathway, IFNAR1 negatively regulates the STAT3 pathway upon binding to IFN1 to accelerate metastasis in endometrial cancer." (PMID 35244291, 2022). "Similarly, the long non-coding RNA NEAT1/miR-361/STAT3 axis drove aggressive endometrial cancer progression." (PMID 33896365, 2021). "Other studies have shown that conditioned medium from endometrial cancer cell‐pretreated adipose‐derived stem cells (ADSCs) promotes endometrial cancer cell proliferation and migration by activating the STAT3 signaling pathway, which suggests that ADSCs are context‐dependent by the tumor milieu." (PMID 34014590, 2021). "Moreover, high glucose can promote the proliferation of endometrial cancer cells by activating STAT3 expression, which can be inhibited by metformin." (PMID 31440472, 2019). "STAT3 activation has been reported to suppress miR-204 expression in endometrial carcinoma cells." (PMID 30867423, 2019). "Indeed, overexpression and constitutive activation of STAT3 have been found in multiple types of tumors, including endometrial cancer." (PMID 30586414, 2018). "We have previously demonstrated that IL11 promotes endometrial cancer cell migration in vitro, via STAT3 and that blockade of IL11 receptor (R) α reduces grade-1 and grade-2 derived human endometrial epithelial cell line xenograft tumour growth and metastasis in mouse models." (PMID 28186993, 2017). "In the human endometrium and placenta, IL11 activates the janus kinase and signal transducers and activators of transcription (JAK/STAT3) pathway STAT3 is constitutively active in many human cancers, including endometrial cancer and has the capacity to promote epithelial tumour growth." (PMID 28186993, 2017). "Given that STAT3 is over-expressed in endometrial cancer and hyperglycemia has been shown to activate the STAT3 pathway in another disease site, we investigated whether high glucose concentrations might have an impact on STAT3 in endometrial cancer." (PMID 28114390, 2017). "Furthermore, autocrine hGH-induced proliferative and anti-apoptotic effects have been shown to be mediated by the JAK2/STAT3 signaling pathway in endometrial carcinoma." (PMID 28617312, 2017). "STAT3 has been reported to mediate the oncogenic actions of hGH in endometrial carcinoma cells." (PMID 29262609, 2017). "Similarly, activation of STAT3 has been shown to downregulate miR-204 expression in nasopharayngeal carcinoma and endometrial carcinoma." (PMID 27438705, 2016). "We demonstrate a role for miR-204-5p in endometrial cancer and also shed light on a novel posttranscriptional regulatory circuit in which TrkB induces the activation of STAT3 to regulate the expression of miR-204-5p, which in turn, directly modulates TrkB expression in endometrial cancer cells." (PMID 24321270, 2013). "Moreover, inhibition of STAT3 by small interference RNA (siRNA) elevated the miR-204-5p expression in IshikawaTrkB and HEC-1B cells (P < 0.05), indicating that, indeed, TrkB activates the JAK2/STAT3 pathway in endometrial cancer cells." (PMID 24321270, 2013). "STAT3 is classified as a proto-oncogenic transcription factor, and constitutive activation of STAT3 has been frequently detected in various types of human cancers including endometrial carcinoma." (PMID 24321270, 2013). "In addition, this study provides a comprehensive mechanism in the tumorigenesis of endometrial carcinoma for TrkB in inducing phosphorylation of STAT3 to regulate the expression of miR-204-5p, which, in turn, controls TrkB expression." (PMID 24321270, 2013). "Whether IL11 alone activates STAT3 phosphorylation in endometrial cancer cells remains to be elucidated." (PMID 20553623, 2010).
endometrial cancer (continued). "Our data strongly support the possibility that the activated Stat3 pathway could serve as a therapeutic target in cervical and possibly in endometrial cancers using a dominant-negative Stat3 mutant or small molecular inhibitors." (PMID 17311011, 2007). "How Stat3 is activated in endometrial cancer is currently unknown and it will be of interest to further examine the mechanisms." (PMID 17311011, 2007). "We first examined the phosphorylation of Stat3 in endometrial cancer specimens." (PMID 17311011, 2007). "The constitutive Stat3 signaling may be a novel therapeutic target for cancer intervention in cervical and endometrial carcinomas." (PMID 17311011, 2007). "Similarly, PTPRD acts via a STAT3 pathway that is activated in endometrial cancer." (PMID 38339334, 2024). "In the treatment of lipid metabolism in endometrial cancer, micronized estradiol and progesterone are combined to treat early endometrial cancer (IA/G1 stage), and silibinin can effectively inhibit the proliferation of cancer cells by inhibiting the expression of STAT3 phosphorylation." (PMID 36072980, 2022). "We also showed that CD146+CAFs promoted the progression of endometrial cancer by inducing angiogenesis and VM via the IL-10/JAK1/STAT3 pathway in vitro and in vivo exploration." (PMID 38459564, 2024). "IL-10 promoted epithelial-endothelial transformation (EET) and further VM formation in endometrial cancer cells via the janus kinase 1/signal transducer and activator of transcription 3 (JAK1/STAT3) signalling pathway." (PMID 38459564, 2024). "LncRNA is involved, among others, in initiating a prometastatic endometrial cancer phenotype; nuclear paraspeckle assembly transcript 1 (NEAT1)-mediated miR-361 sponging activates the STAT3 axis." (PMID 39188680, 2024). "Taken together, we demostrate that CD146+CAFs can promote progression of endometrial cancer by inducing angiogenesis and vasculogenic mimicry via IL-10/JAK1/STAT3 pathway." (PMID 38459564, 2024). "Recently, it has also been demonstrated that miR-182-5p targeted PIAS1 (protein inhibitor of activated STAT) mRNA in endometrial cancer, and the overexpression of PIAS1 inhibited Stat3 activity." (PMID 37887350, 2023). "The inflammatory pathways predominantly reported in the literature on progression of endometrial cancer are the MAPK, JAK/STAT3 and PI3K/AKT /mTOR pathways." (PMID 34951691, 2022). "ovarian and endometrial cancers: curcumin suppresses JAK-STAT signaling via activation of PIAS-3, thus attenuating STAT-3 phosphorylation and tumor cell growth." (PMID 32927725, 2020). "miR-204-5p has been shown to suppress the growth, migration and invasion of endometrial carcinomas by binding to TrkB mRNA and interfering with JAK2 and STAT3 phosphorylation." (PMID 28621736, 2017). "In endometrial cancer, OSM was shown to activate STAT3, enhance cell migration and invasion in vitro and promote cell proliferation, growth and angiogenesis in vivo." (PMID 27918443, 2016). "It indicates that IL11, along with its specific receptor, IL11Rα, and downstream signalling molecules, STAT3 and SOCS3, are likely to play a role in the progression of endometrial carcinoma." (PMID 20553623, 2010). "In addition, we assessed the Janus kinases/signal transducer and activator of transcription 3 (JAK/STAT3) pathway, which is constitutively activated in endometrial cancer and plays a key role in tumor growth and progression." (PMID 41303544, 2025). "IL-6, as a multifunctional factor, promotes endometrial cancer, not only in relation to JAK/STAT3." (PMID 39188680, 2024). "Interestingly, miR-20a-5p's function seems to vary based on tissue context; for example, in endometrial cancer, miR-20a-5p inhibits EMT by targeting STAT3." (PMID 38561726, 2024). "Taken together, these results provide evidence that CD146+CAFs could promote the progression of endometrial cancer by inducing angiogenesis and VM formation via the IL-10/JAK1/STAT3 pathway." (PMID 38459564, 2024).
endometrial cancer (continued). "KEGG analysis of stage I endometrial carcinomas vs. atrophic endometrium revealed staphylococcus aureus infection, estrogen signaling pathway, IL-17 signaling pathway, Renin secretion, inflammatory response, JAK/STAT3, K-Ras, and TNFα/NF-κB." (PMID 37958433, 2023). "However, in endometrial cancer, MUC20 overexpression drives tumourigenesis, predicts poor survival, and EGF-induced malignant phenotypes were enhanced by activating the EGFR/STAT3 pathway." (PMID 36059804, 2022). "In addition, we also found that miR-326@SPION can efficiently inhibit the expression of the GPR91/STAT3/VEGF signalling pathway and weaken the in vivo and in vitro viability of endometrial cancer stem cells." (PMID 32174801, 2020). "Subsequent studies have shown that changes in the expression of AKT1, p70S6K, rpS6, GSK3beta, signal transducer and activator of transcription 3 (STAT3), and B-cell lymphoma-extra large (BCl-xl) were correlated with changes of lncRNA, DLEU1, and mTOR in endometrial carcinoma." (PMID 31947591, 2020). "The work of Tsai and colleagues demonstrated that STIP1 physically interacts with STAT3 in ovarian and endometrial cancer cells and is essential in the assembly and stabilization of the JAK2-HSP90-STAT3 complex, which promotes STAT3 phosphorylation and signal transduction." (PMID 29914167, 2018). "In addition, we have shown that metformin-mediated induction of cell death might not completely depend on STAT3 inhibition in type 1 endometrial cancer cells." (PMID 28114390, 2017). "The effect of IL11 on pSTAT3/STAT3 and SOCS3 protein abundance in endometrial cancer cell lines and non-cancer endometrial epithelial cells was determined by Western blot." (PMID 20553623, 2010). "IL11, IL11 receptor(R) α, phosphorylated (p) STAT3 and SOCS3 were examined by immunohistochemistry in endometrial carcinomas and in control endometrium from postmenopausal women and normal cycling women." (PMID 20553623, 2010).
inflammatory bowel disease (87 papers, 2009 to 2026). A spectrum of small and large bowel inflammatory diseases of unknown etiology. "Persistent or dysregulated activation of STAT3 has been linked to multiple chronic inflammatory conditions, such as asthma, inflammatory bowel disease (IBD), and other inflammatory disorders." (PMID 40166646, 2025). "Classic signaling pathways, such as NF-κB, PI3K/AKT, and STAT3, play a crucial role in inflammation and the development of colorectal cancer associated with inflammatory bowel disease (IBD)." (PMID 38892375, 2024). "Genome-wide association studies (GWAS) have revealed the role of STAT3 in diseases like mean corpuscular volume, multiple sclerosis, inflammatory bowel disease, Crohn disease, ankylosing spondylitis, psoriasis, ulcerative colitis, and sclerosing cholangitis." (PMID 37860678, 2023). "STAT3 targets were significantly enriched for genes associated with inflammatory bowel disease (IBD), as well as the two IBD-subtypes, Crohn's disease and ulcerative colitis." (PMID 30696696, 2019). "Genome wide association studies (GWAS) have also linked a STAT3 polymorphism to inflammatory bowel diseases (IBD)." (PMID 31799221, 2019). "STAT3 has been reported in several previous genome-wide association studies (GWAS) to be associated with immune relevant diseases such as Crohn’s disease, inflammatory bowel disease, and multiple sclerosis." (PMID 26621531, 2016). "Genome-wide association studies have identified a certain correlation between STAT3 and the susceptibility to inflammatory bowel disease (IBD)." (PMID 38520006, 2024). "STAT3 is momentarily active in healthy cells, but continuously triggered STAT3 is linked to inflammatory bowel disease (IBD), which modifies the response of gut immune cells." (PMID 36497125, 2022). "Inflammatory bowel disease (IBD) is intricately linked to dysregulated immune responses within the gastrointestinal tract, where the JAK2/STAT3 pathway assumes a pivotal role." (PMID 39187810, 2024). "In this context, Stat3 whose function is increased by CD5 deficiency had previously been described as a critical regulator of the Th17/Treg balance, particularly in inflammatory bowel disease." (PMID 35720357, 2022). "On protein level, the key proteins like IL-6, TNF-α, NFKBp65, and STAT3 of the inflammatory bowel disease pathway had the same change trend." (PMID 36382627, 2022). "Curcuma relieved the colon inflammation of ulcerative colitis via inactivating TNF pathway, inflammatory bowel disease pathway, and epithelial cell signaling in Helicobacter pylori infection pathway, probably by binding to STAT3 and TNF-α." (PMID 34221084, 2021). "Studies have shown that STAT3 (signal transducer and activator of transcription 3) activation contributes to inflammatory bowel disease and CRC." (PMID 31540435, 2019). "Stat3 is a transcription factor whose increased activation in colonic epithelial cells has been observed in some patients with active inflammatory bowel disease (IBD)." (PMID 25799189, 2015). "Using a mouse model of inflammatory bowel disease, we recently suggested a role of Stat3 (signal transducer and activator of transcription 3) activation in intestinal epithelial cells (IECs) for tissue homeostasis." (PMID 25799189, 2015). "Shikonin acts by blocking the activation of two major targets: NF-κB and STAT-3, and thus constitutes a promising potential therapeutic agent for the management of the inflammatory bowel disease." (PMID 23346196, 2012). "Additionally, IL-6 can promote the development of inflammatory bowel disease through the STAT3 signaling pathway." (PMID 40053041, 2025). "Phosphorylated STAT3 then dimerizes, translocates, and binds to DNA, resulting in the production and release of inflammatory factors IL-17, IL-21, and IL-22, collectively influencing inflammatory bowel diseases like UC." (PMID 40446056, 2025).
inflammatory bowel disease (continued). "IRF4 is involved in the pathological process of a variety of inflammatory diseases, including the promotion of interleukin(IL)-6 production in inflammatory bowel disease, which induces STAT3 expression in T lymphocytes to promote apoptosis followed by intestinal inflammation." (PMID 38195465, 2024). "To further clarify the mechanism of action of YHKJ combined with SASP in the treatment of UC, we performed KEGG network pharmacologyanalysis and found that STAT3, a core target, is involved in the pathological changes in UC in the inflammatory bowel disease pathway." (PMID 39318778, 2024). "STAT3, a pleiotropic transcription factor, plays a critical role in the pathogenesis of autoimmunity, cancer, and many aspects of the immune system, as well as having a link with inflammatory bowel disease." (PMID 37860678, 2023). "Taken together, our data indicate that ethanol extract of avocado may be used as a promising therapeutic against inflammatory bowel diseases by suppressing the NF-κB and STAT3 signaling pathway." (PMID 30621304, 2019). "Recent studies have shown that matrine can diminish inflammatory responses and oxidative stress by blocking the IL-6/STAT3 signaling pathway, thereby attenuating intestinal mucosal damage in rats with inflammatory bowel disease (IBD)." (PMID 39902829, 2025). "Since increased STAT3 activation and Th17 cell population are markers of inflammatory bowel disease (IBD), the expression of Zdhhc7 and STAT3 target genes were studied in patients with IBD." (PMID 36467682, 2022). "A recent study in mice showed that PF extract ameliorated inflammatory bowel disease (IBD) via protection of dextran sulfate sodium-induced murine colitis, with NF-κB and signal transduction and activator of transcription 3 (STAT3) as putative targets." (PMID 30597896, 2018). "Several IEC signature TFs have known associations with human Inflammatory Bowel Diseases (IBD), including SMAD7, CEBPG, STAT3, XBP1, HNF4A, ELF3, IRF1, and NFκB components IKBKB, IKBKG, and NFKBIZ." (PMID 28850571, 2017). "It has been previously reported that IL-22, one of the cytokines secreted by Th17 cells, demonstrates both a protective and inflammatory promotion effect in inflammatory bowel disease (IBD) through STAT3 signaling activation." (PMID 23379788, 2013). "Among these, the core pathway related to UC was inflammatory bowel disease (KEGG:05321), containing the hub targets of IL6, TNF, RELA, and STAT3." (PMID 36382627, 2022). "The core pathway related to UC was inflammatory bowel disease referring to IL6, TNF, RELA, and STAT3." (PMID 36382627, 2022). "Resveratrol also protected inflammatory bowel disease and improved gut barrier function by downregulating the expression of HIF-1, mTOR, and STAT3 pathway." (PMID 32973502, 2020). "In mouse models of inflammatory bowel disease (IBD), Dusp2−/− mice developed more severe inflammatory disease, with increased production of Th17 cells via STAT3 signaling." (PMID 31159473, 2019). "STAT3 is an important transcription factor in the JAK/STAT pathway and has been shown to be affected in inflammatory bowel disease (IBD)." (PMID 24283712, 2013). "In humans STAT3 represents one of the disease loci for Crohn's and inflammatory bowel disease (IBD), and most likely relates to the capacity of Stat3 to promote intestinal barrier function and integrity in response to IL6, IL11 and IL22 exposure." (PMID 20478049, 2010). "Furthermore, it may impede STAT3 and Th17 activation in individuals with inflammatory bowel disease (IBD), thereby providing an explanation for the observed protective impact of this variant." (PMID 39796684, 2024). "Besides being highly expressed in pancreatic tissue, Reg proteins were also found to be inducible in the intestinal tract, particularly Reg1 and Reg3 subfamily proteins that were induced by IL6/IL22 in inflammatory bowel disease (IBD) for mucosal regeneration through STAT3 activation." (PMID 39857608, 2024).
inflammatory bowel disease (continued). "However, F. prausnitzii has been shown to produce butyrate resulting in an anti-inflammatory role by inhibiting interleukin (IL-6), the activator of transcription 3 (STAT3)/IL-17 pathway in colorectal colitis having an important role in inflammatory bowel disease (IBD) treatment." (PMID 36671749, 2022). "Consistent with a protective role of IL-10 in inflammatory bowel diseases (IBD), effector CD4+ T cells from Crohn’s disease patients were defective in Notch/STAT3-induced IL-10 production and skewed towards an inflammatory Th1/17 cell phenotype." (PMID 35169232, 2022). "These include inflammatory bowel disease (IBD) and its more severe phenotype, Crohns disease, with SOCS3 responsible for suppressing the activation of inflammatory genes induced by STAT3 during IBD." (PMID 34604264, 2021). "In laminar propria lymphocytes of inflammatory bowel disease patients, LIF-activated STAT4 inhibits activation of the STAT3-dependent Il17a/Il17f promoter, while in intestinal epithelial cells, LIF bypasses abnormally low STAT4 levels and induces YAP gene expression by activating STAT3." (PMID 33505963, 2020). "We sought to determine whether metformin reduces inflammation, by regulating p-signal transducer and activator of transcription 3 (STAT3) expression and T-helper 17 (Th17) cell proliferation, in a mouse model of inflammatory bowel disease (IBD)." (PMID 26360050, 2015).